MMP8 (matrix metallopeptidase 8)
Diseases named in the same sentence as MMP8 in open-access papers (continued):
Sharing a sentence is not in itself a finding about the gene and the disease.
breast carcinoma (continued). "Moreover, MMP8 rs11225395 CT + TT was associated with reduced breast cancer relapse (p = 0.04), greater overall HR = 0.7, 95% CI 0.5–1.0, p = 0.02) and disease-free survival (HR = 0.7, 95% CI 0.5–0.9, p = 0.02) among women with stage 0–II cancer in the Shanghai Breast Cancer Study." (PMID 36009438, 2022). "We aimed to evaluate the contribution and association of single-nucleotide polymorphisms (SNPs) in MMP genes (MMP1, MMP2, MMP3, MMP7, MMP8, MMP9) with clinicopathological breast-cancer features." (PMID 36009438, 2022). "Mouse models suggest that high MMP8 expression reduced metastasis formation in melanoma and breast cancer and diminished the migratory and invasive potential of melanoma and breast cancer cells in vitro." (PMID 34059618, 2021). "Accordingly, MMP8 overexpressing breast cancer cells had reduced migratory and proliferative properties in vitro." (PMID 31514474, 2019). "For example, MMP-8 expression has been shown to induce the expression of pro-inflammatory factors by breast cancer cells." (PMID 30970007, 2019). "Although the expression of MMP-8 is detrimental to breast cancer cells, MMP-8 upregulates pro-tumor cytokines, IL-6 and IL-8, in a self-reinforcing loop manner." (PMID 31010242, 2019). "Although MMP8 was mainly found to be expressed by metastatic cell lines and not the non-metastatic MCF-7 cell line, many have shown that MMP8-expressing breast cancer cell lines are less invasive in vitro and generate less metastases in mice in vivo." (PMID 31514474, 2019). "Overall MMP levels increase during malignant transformation in breast cancer cell lines—so does MMP8 as well." (PMID 31514474, 2019). "The role of MMP8 seems more definite in those cancers, that are well studied—e.g., the effects of MMP8 in breast cancer is studied in more than 30 research articles." (PMID 31514474, 2019). "MMP8 and MMP9 have been shown to be associated with breast cancer (BC) risk in European and American populations." (PMID 30194384, 2018). "MMP-8 appears to downregulate the TGF-β signalling evident in DCIS-associated MEC, and opposes MMP-9 activity, which we show promotes breast cancer cell invasion and also has been shown to prevent HD formation." (PMID 28330493, 2017). "A significant reduction in the number of breast cancer cells invading through Matrigel in the presence of β6-1089 cells expressing MMP-8 WT was observed compared to cells transfected with EA or empty vector." (PMID 28330493, 2017). "There is a growing body of evidence accumulating that MMP-8 has an anticancer role in breast cancer, malignant melanoma and tongue squamous cell carcinoma." (PMID 28330493, 2017). "A high plasma level of MMP-8 has been shown to be protective against lymph node metastasis in breast cancer patients." (PMID 26155333, 2015). "We recently reported that enhanced production of MMP-8 by breast cancer cells induced the expression of the proinflammatory mediators interleukin-6 (IL-6) and IL-8." (PMID 25848906, 2015). "Xenograft models with breast cancer and melanoma cells have also demonstrated the anti-metastatic ability of MMP-8." (PMID 25848906, 2015). "Our observations in the MMTV-PyMT mouse mammary cancer model concur with observations of a suppressive role for host-derived MMP-8 in carcinogen-induced skin tumorigenesis." (PMID 25848906, 2015). "Together these findings confirm the anti-tumorigenic and anti-metastatic functions of MMP-8 in a spontaneous mouse mammary cancer model and highlight its impact on multiple components, including angiogenesis and inflammatory cell involvement." (PMID 25848906, 2015). "Subsequently, MMP-8 expression was found to be a marker of a lower incidence of lymph node metastasis and, consequently, to confer a better prognosis in human breast carcinoma." (PMID 23632023, 2013). "We explored the effects of expression of either a WT or catalytically inactive (E198A) mutant version of MMP-8 in human breast cancer cell lines." (PMID 23632023, 2013).
breast carcinoma (continued). "We do not yet know the identities of the molecules that confer the continued ability of breast cancer cells to grow while expressing catalytically active MMP-8." (PMID 23632023, 2013). "In conclusion, therefore, our experiments reveal a novel action of catalytically active MMP-8 in breast cancer cells that results in increased production of key regulators of tumor growth and inflammation, IL-6, and IL-8." (PMID 23632023, 2013). "In turn, IL-6 enhances endogenous MMP8 expression in breast cancer cells, and IL-8 is responsible in part for the increased expression of IL-6." (PMID 23632023, 2013). "One of the most important points to emerge from this study is that sustained, elevated expression of MMP-8 by breast cancer cells eventually impaired their growth." (PMID 23632023, 2013). "In breast cancer, MMP-8 changes metastatic potential in vitro, and in melanoma and lung cancer it inhibits metastasis formation by modulating cancer cell invasion and adhesion." (PMID 23216739, 2012). "In contrast to this, we found a significant higher expression of pro- and active MMP-8 in breast cancer compared to normal breast tissue." (PMID 19531263, 2009). "In summary, we observed differences in MMP1 and MMP8 plasma levels between healthy controls and breast cancer patients as well as between breast cancer patients." (PMID 18366705, 2008). "This study aimed at evaluating plasma levels of MMP1, MMP8 and MMP13 as diagnostic and prognostic markers of breast cancer." (PMID 18366705, 2008). "In this study, we evaluated the usefulness of circulating MMP1, MMP8 and MMP13 levels as diagnostic and prognostic markers in breast cancer." (PMID 18366705, 2008). "Different studies suggest that high MMP8 protein levels might predict better survival in tongue cancer patients and some breast cancer patients but provide a worse prognosis in hepatocellular and ovarian cancers." (PMID 38474106, 2024). "In breast cancer, MMP-8 and -12 have exhibited anti-tumorigenic effects in vivo." (PMID 36741729, 2022). "Also, the overexpression of MMP-8 in metastatic breast cancer cells reduces their metastatic potential, and higher MMP-8 expression is correlated with the lower incidence of lymph node metastasis and good prognosis." (PMID 35201460, 2021). "However, it has been suggested that MMP-8 has a tumor suppressive role in breast cancer cells that, in contrast to gastric and liver tumors, leads to inhibition of migration, invasion and metastasis, both in vitro and in vivo." (PMID 34884877, 2021). "In breast cancer patients, serum MMP8 levels were higher compared to healthy controls." (PMID 31514474, 2019). "Furthermore, MMP8 overexpression was shown to increase the expression of interleukins 6 and 8 in breast cancer cells, which was postulated to be connected to inflammatory response rather than cancer progression." (PMID 31514474, 2019). "While the role of MMP8 has provoked some controversy in which some studies reported its effect on cytokine release in the cancer microenvironment in breast cancer and some ovarian cancer cell lines, other reports have shown that MMP8 possess some antitumor properties." (PMID 29320405, 2018). "The biological significance of loss of MEC-derived MMP-8 on MEC phenotype and MEC-breast cancer cell crosstalk remains elusive, especially whether MMP-8 may contribute to the tumour-suppressor function of MECs." (PMID 28330493, 2017). "When the MMP-8 substrate Col-I was replaced with Matrigel in transwell invasion assays, there also was a significant downregulation in breast cancer cell invasion towards MMP-8 WT over-expressing β6-1089 cells, but not MMP-8 EA or empty vector transfected cells (data not shown)." (PMID 28330493, 2017). "MMP-8 expression can be used as a good prognostic marker in breast cancer, while MMP-3, MMP-11, and MMP-19 have been found to play dual roles in cancer, and they may exert protumorigenic or suppressor roles depending on the tumor context." (PMID 24578639, 2014).
breast carcinoma (continued). "It has recently been described that MMP-8 expression in breast cancer cells provokes a reduction in the microRNA-21 (miR-21), which may predict a recurrence and unfavorable survival in nonsmall cell lung cancer." (PMID 24578639, 2014). "Thus, the induction of IL-6 and IL-8 expression attributable to the catalytic activity of MMP-8 in breast cancer cells is consistent with a role for MMP-8 in the initial triggering of an acute inflammatory response." (PMID 23632023, 2013). "On the basis of the known tumor- or metastasis-suppressive effects of MMP-8 in several cancers and its links to inflammatory responses, we sought to explore in more detail its actions on cytokine and chemokine networks elaborated by breast cancer cells." (PMID 23632023, 2013). "Moreover, the present data exemplify the puzzling dual role of MMP8 in breast cancer as both pro- and anti-tumorigenic/metastatic." (PMID 18366705, 2008). "The presence of cancer seems to increase the level of MMP8 in circulation and depending on the cancer, high plasma MMP8 levels might be beneficial (e.g., breast cancer), but in some cancers (colorectal, hepatocellular and melanoma) high serum MMP8 levels correlate with poor prognosis." (PMID 31514474, 2019). "In the present study, we have explored the effects of constitutional loss of MMP-8 on mammary oncogenesis and metastasis in the mouse mammary tumor virus-Polyoma virus middle T-antigen (MMTV-PyMT) mouse, which is a rapid and robust model of human luminal breast cancer." (PMID 25848906, 2015). "However, sustained expression of WT MMP-8 was deleterious to breast cancer cell growth in colony formation assays, and, upon extended culture, the exogenous MMP8 expression cassette was silenced in most cell pools, accompanied by a coordinate reduction in IL-6 and IL-8 expression." (PMID 23632023, 2013). "Interestingly, our results suggest that MMP8 may affect the metastatic behaviour of breast cancer cells through protection against lymph node metastasis, underlining the importance of anti-target identification in drug development." (PMID 18366705, 2008). "This hypothesis has been put forward by Montel and colleagues who recently reported that reducing MMP8 levels by the ribozyme knock-down technique dramatically increased lymph node metastasis of breast cancer cells orthotopically implanted in mice but has a smaller effect on metastasis to the lung." (PMID 18366705, 2008). "Tumor-associated neutrophils by secreting the cytokine tissue inhibitor matrix metalloproteinase 1 (TIMP-1) induce breast cancer EMT and can also remodel the extracellular matrix via neutrophil collagenase (MMP8) and gelatinase B (MMP9)." (PMID 38715921, 2024). "In breast cancer patients, expression of MMP-8 correlates with lower lymph node metastasis, which indicates MMP-8 as a potential prognostic marker for breast cancer patients." (PMID 31010242, 2019). "Analysis of serum-free conditioned media from three breast cancer cell lines (MCF-7, SK-BR-3, and MDA-MB-231) expressing WT MMP-8 revealed elevated levels of IL-6 and IL-8." (PMID 23632023, 2013). "Our study demonstrates how the activation of an IE near the MMP8 gene determines the regional transcriptional regulation of MMP genes with opposing functional activity, ultimately influencing the invasive properties of aggressive forms of breast cancer." (PMID 38017545, 2023). "Co-culture with adipose tissue-derived mesenchymal stem cells, a driver of tumorigenesis, did not affect the MMP8 expression of breast cancer cells." (PMID 31514474, 2019). "MMP8 expression in plasma was higher in patients with non-inflammatory breast cancer as well as in patients with lymph node involvement, but interestingly, lower in patients with risk of distant metastasis." (PMID 31514474, 2019). "MMP-8 WT but not MMP-8 EA over-expression in β6-1089 reduced breast cancer cell invasion in 2D and 3D invasion assays, while MMP-8 knock-down in N-1089 enhanced cancer cell invasion." (PMID 28330493, 2017).
breast carcinoma (continued). "This demonstrated that breast cancer cell invasion was significantly enhanced in the absence of MMP-8." (PMID 28330493, 2017). "We show here that expression of catalytically active MMP-8 leads to increased production of the proinflammatory mediators IL-6 and IL-8 in multiple breast cancer cell lines but not in normal mammary epithelial cells." (PMID 23632023, 2013). "Similar results were obtained with another breast cancer cell line (SK-BR-3) transiently transfected with WT MMP-8 and E198A MMP-8, but this phenomenon was not seen on transient transfection into a non-cancerous breast epithelial cell line, HMT-3522 S1 (D)." (PMID 23632023, 2013). "This study extends these findings using a series of human mammary carcinoma cell lines, where we demonstrate that transient expression of catalytically active WT MMP-8, but not an inactive E198A mutant form, induced the expression of IL-6 and IL-8." (PMID 23632023, 2013). "Similar MMP8 expression was found in plasma from healthy controls and breast cancer patients without lymph node involvement (pN0)." (PMID 18366705, 2008). "Plasma MMP1 and MMP8 levels did not correlate among controls (rs = 0.10, p = 0.54, data not shown) nor among breast cancer patients (rs = 0.009, p = 0.90, data not shown)." (PMID 18366705, 2008). "Thus, MMP8 expression, although low in non-malignant breast cancer cells, seems to act as a tumor suppressor rather than an enhancer in malignant cells but not in neutrophils." (PMID 31514474, 2019). "Overall these data indicate that MEC-derived MMP-8 acts as a tumour suppressor by promoting HD formation and enhancing cell adhesion to ECM, thus maintaining tissue architecture, and concomitantly downregulating breast cancer cell invasion in a proteolytic-dependent manner." (PMID 28330493, 2017). "However, we also show that expression of catalytically active MMP-8 is not sustainable in breast cancer cells in long-term culture without additional stochastic events that allow the emergence of high-expressing clones." (PMID 23632023, 2013). "Accordingly, a microarray analysis of the epigenetic regulation of MMPs in breast cancer and glioma cell lines revealed an epigenetic inactivation of MMP8 unlike other MMPs, which could explain the reduction of active MMP8 in various malignancies unrelated to their genetics." (PMID 31514474, 2019). "However, sustained expression of WT MMP-8 by breast cancer cells was non-permissive for long-term growth, as shown by reduced colony formation compared with cells expressing either control vector or E198A mutant MMP-8." (PMID 23632023, 2013). "Levels of MMP-8 and -9 correlated significantly with each other and with TIMP-1 levels, but were not related to tumour size or prognosis in human breast cancer." (PMID 16940985, 2006). "However, MMP8 was shown not to be involved in the tumor-promoting effects of TLR9 and relaxin that induced the activity of many MMPs in breast cancer cells thereby increasing cell invasiveness." (PMID 31514474, 2019). "Additionally, plasma MMP-8 levels are not specific for IPF as increased plasma MMP-8 levels occur in patients with active coronary artery disease and breast cancer." (PMID 24828408, 2014).
atherosclerosis (35 papers, 2011 to 2025). A disease characterized by the build-up of fatty material and calcium deposition in the arterial wall resulting in partial or complete occlusion of the arterial lumen. "To study the effects of MMP8 deficiency in MF on atherosclerosis, we irradiated Apoe-/- or MMP8KO/Apoe-/- mice and performed bone marrow transplantation (BMT)." (PMID 40991633, 2025). "There are other MMPs implicated in atherosclerosis, but MMP8 is one of the only MMPs that has similar levels of expression in macrophages in both humans and mice." (PMID 40991633, 2025). "A marker of atherosclerosis, elevated level of matrix metalloproteinase 8 (MMP-8), was also strongly linked to FH gene polymorphisms in a large unbiased population study." (PMID 31428091, 2019). "Knockdown of MEF 2A enhanced MMP-8 expression and decreased collagen content in the carotid plaques, which was in line with previous studies indicating that atherosclerosis in the MMP-8 deficient mice had increased collagen content." (PMID 25793529, 2015). "Considering the multifactorial causes of atherosclerosis, it is probably too simplistic to assume that a single systemic or intraplaque biomarker (i.e., MMP-8) would suffice as a pathophysiological target for treatments and diagnosis." (PMID 23365489, 2013). "They generated ApoE−/− MMP-8−/− mice to support a pathogenic role for MMP-8 in the development and progression of atherosclerosis." (PMID 23365489, 2013). "So, the results obtained in these “large” studies indicated that the plasma MMP-8 concentrations in patients with advanced atherosclerosis have been positively associated with the presence and severity of carotid artery plaque progression." (PMID 23365489, 2013). "In summary, this genetic approach has demonstrated a significant relationship between a MMP-8 gene polymorphism and the progression of atherosclerosis." (PMID 23365489, 2013). "In addition, the occurrence of atherosclerosis was positively associated with serum MMP8 concentration that increased the expression of vascular cell adhesion molecule-1 (VCAM-1)." (PMID 35145983, 2022). "A demonstrated relationship between the variability of the MMP-8 gene and atherosclerosis suggest that MMP-8 concentrations may have prognostic and diagnostic significance in assessing the patient’s cardiovascular risk." (PMID 32486345, 2020). "In addition, the association between MMP-8 gene variation and atherosclerosis was validated in several population-based studies." (PMID 23365489, 2013). "MMP-8 is reported to be associated with both atherosclerosis and metabolic syndrome." (PMID 23637817, 2013). "Therefore, we aimed to test whether MMP8 deficiency specifically in MF would affect atherosclerosis." (PMID 40991633, 2025). "The increased MMP-8 may promote weight gain and insulin resistance in obese individuals by cleaving and degrading the human insulin receptor, making obese patients more susceptible to atherosclerosis and increasing long-term mortality." (PMID 39609876, 2024). "A previous study showed that global knockout of MMP8 results in increased collagen deposition and reduced atherosclerosis." (PMID 40991633, 2025). "MMP8 is expressed by many plaque cell types, but as macrophages are the major source of MMP in atherosclerosis, we first wanted to investigate the role of MMP8 derived from macrophages and how IGF-1 influences MF phenotype." (PMID 40991633, 2025). "Our results establish the importance of MF MMP8 as a potential target to treat unstable atherosclerosis." (PMID 40991633, 2025). "We also found that MF IGF-1 overexpression reduces MMP8 levels in atherosclerotic plaque in a mouse model of atherosclerosis." (PMID 40991633, 2025). "MMP‐8 contributes to vascular remodeling, atherosclerosis, and plaque instability, linking MetS to periodontal tissue destruction and systemic complications." (PMID 38852177, 2025).